RNU6-1268P (RNA, U6 small nuclear 1268, pseudogene)
Gene: Small nuclear RNA gene on chromosome 14 (19,422,815 to 19,422,921, reverse strand). Ensembl gene ENSG00000212516.
Homologues: Orthologues: chimpanzee U6 (97% identical), chimpanzee U6 (96% identical), macaque U6 (95% identical), chimpanzee U6 (94% identical), macaque U6 (93% identical), guinea pig U6 (77% identical), dog U6 (76% identical), pig U6 (65% identical). Paralogues in human: RNU6-1239P (100% identical), RNU6-816P (100% identical), RNU6-473P (98% identical), RNU6-617P (98% identical), RNU6-848P (98% identical), RNU6-1049P (97% identical), RNU6-127P (97% identical), RNU6-1021P (93% identical), RNU6-286P (93% identical), RNU6-631P (93% identical), RNU6-749P (93% identical), U6 (93% identical), and 1286 more.